CCL2 (C-C motif chemokine ligand 2)
Diseases named in the same sentence as CCL2 in open-access papers (continued):
Sharing a sentence is not in itself a finding about the gene and the disease.
diabetic neuropathy (8 papers, 2015 to 2025). A chronic, pathological complication associated with diabetes mellitus, where nerve damages are incurred due to diabetic microvascular injury involving small blood vessels that supply these nerves, resulting in peripheral and/or autonomic nerve dysfunction. "In rats with diabetic neuropathy, the CCL2 expression level is increased 3–4 weeks after STZ injection in sciatic nerve tissue but not in the spinal cord." (PMID 39457105, 2024). "A model of STZ-induced diabetic neuropathy has revealed increased CCL2 mRNA levels in the lumbar region of the spinal cord in male mice on day 7 after STZ injection, which was confirmed by our recent study." (PMID 39457105, 2024). "For example, CCL2, S100A12, and matrix metalloproteinases are elevated in conditions like diabetic neuropathy, trigeminal neuralgia, and compressive radiculopathies." (PMID 39015317, 2024). "Monocyte chemoattractant protein 1 (CCL2) is a chief mediator of renin angiotensin system cytokines and emerges in the kidneys of diabetic neuropathy patients, leading to end stage renal failure." (PMID 35154608, 2021). "Moreover, CCL-2/MCP-1 and CXCL-10/IP-10 levels were higher in patients with diabetic neuropathy over those with leprosy neuropathy." (PMID 32038662, 2020). "Additionally, it has been shown that CCR5, CCL2, CCL3, CCL5, CCL7, CCL8, and CCL12 spinal mRNA and/or protein levels are elevated in rodent models of diabetic neuropathy, with some displaying sex-related diversity." (PMID 39457105, 2024).
invasive breast carcinoma (8 papers, 2016 to 2023). A carcinoma that infiltrates the breast parenchyma. "Consistent with this, CCL2 has been found to be one of the most strongly downregulated genes in endothelial cells of invasive breast cancer compared to endothelial cells of normal mammary vasculature." (PMID 36374225, 2023). "In invasive breast cancer, CCL2 expression in the stroma correlates with disease recurrence." (PMID 33888841, 2021). "In addition, secretion of CCL2 protein was detected, which is over-expressed in invasive breast cancer and regulates its progression." (PMID 32443890, 2020). "In summary, CCL2 knockdown through delivery of Ca-TAT/siRNA complexes could be an effective treatment strategy for the treatment of invasive breast cancer, particularly when combined with other anti-cancer therapies." (PMID 27283985, 2016). "Addressing these questions would provide an important justification to further develop the CCL2/CCR2 pathway as a predictive signature and in approaches to prevent invasive breast cancer." (PMID 33888841, 2021). "Besides, CDK8 drives the expression of matrix metalloproteinase Mmp9, which contributes to the invasive character of several cancer cell types and regulates Ccl2 in TNBC cells, which has been found overexpressed in invasive breast cancers and is suggested to support metastasis." (PMID 34689158, 2021).
latent infection (8 papers, 2009 to 2023). "In conclusion we have identified an association of elevated CCL-2 plasma levels with latent tuberculosis and a further effect of GG genotype in increasing the risk of latent infection." (PMID 21991356, 2011). "Since the HC group had much higher rate of latent infection compared to EC, these results suggest that the household contacts were at a higher risk of developing latent infection due to the presence of CCL-2 -2518 GG genotype." (PMID 21991356, 2011). "Since CCL2 is released early we have focused on the role of CCL2 in mycobacterial latent infection which is the earliest consequence of susceptibility to infection." (PMID 21991356, 2011). "Our results also suggest a role for CCL-2 in maintaining the integrity of granuloma in asymptomatic individuals with latent infection in high TB burden settings." (PMID 21991356, 2011). "Variable associations in different ethnic population may be due to both variability in the prevalence of latent infection, as well as variability of frequencies of the different CCL-2 genotypes." (PMID 21991356, 2011). "CCL-2 predominantly recruits memory T cells to the site of infection and therefore may play an important role in maintaining the architecture of granuloma in latent infection." (PMID 21991356, 2011). "For instance, CCL-2 was recently shown to mediate early seeding of the HIV reservoir by recruiting a unique subset of CCR2/5+ CD4+ T-cells which become infected and form a significant reservoir for latent infection." (PMID 36992409, 2023). "This means that CCL2 produced by HIV-1-infected macrophages would have the capacity to recruit both monocytes and activated T cells to the site of infection, facilitate the latent infection of resting T cells, and enhance virus replication in activated T cells." (PMID 38005838, 2023).
Listeria infection (8 papers, 2014 to 2023). "CCL2-mediated stimulation of monocytes’ CCR2 chemokine receptor plays a vital role in the innate immune response to Listeria infection, suggesting that modulation of innate immunity could contribute to Akkermansia-induced resistance to this pathogen." (PMID 37424323, 2023). "It has been shown that Kupffer cell activation and macrophage infiltration in response to Listeria infection is mediated by TLR-2 dependent secretion of Cxcl1 and Ccl2 and that the macrophage infiltration is also stimulated by exogenous Ccl2 and Cxcl1 capabilities." (PMID 36650530, 2023).
metastatic carcinoma (8 papers, 2016 to 2024). A carcinoma which has spread from the original site of growth to another anatomic site. "Along similar lines, we recently showed that the oncogene is responsible for CCL2 secretion by pleural metastatic cancer cells, fostering inflammatory MPE formation." (PMID 29445180, 2018). "Remarkably, both CAF phenotypes showed significantly higher expression of CCL2 compared with primary or metastatic carcinoma cells, which is consistent with scRNA-Seq data and moderate correlations between iCAF or myCAF transcript markers and CCL2 in human PDA." (PMID 36256464, 2022). "Besides, macrophage infiltration has be stunted after blocking the binding of MCP-1 to monocytes expressing the receptor of CCL2 (CCR2), which let mice to delay the progression of metastatic cancer and extend survival." (PMID 28207826, 2017). "We compared the expression differences between metastatic cancer and primary cancer and found that, apart from a significant downregulation of CXCL14 and CCL28, as well as a significant upregulation of CXCL12 and CCL2, the expression levels of most chemokines did not achieve a twofold change." (PMID 39409185, 2024).
peripheral arterial disease (8 papers, 2011 to 2025). A disorder of the arteries supplying the upper and lower extremity and the visceral organs. "Plasma levels of CCL2 are higher in patients with peripheral arterial disease." (PMID 22110589, 2011). "Our research group has paid special attention to investigating the potential utility of CCl2, PON1, and associated metabolic alterations as markers in the diagnosis of peripheral arterial disease (PAD) of the lower extremities." (PMID 34356595, 2021). "In addition, in peripheral artery diseases, activated platelets are enriched in MRP14, which increases their P-selectin expression and the formation of MPAs, and promotes the monocyte inflammatory profile by increasing IL1B, CCL2, and TNFA mRNA levels." (PMID 37279077, 2023).
psychosis (8 papers, 2013 to 2025). "Trait markers which differentiate psychosis patients from healthy controls throughout the illness course were increased CRP, CCL2, and IL1RA, and decreased KA and KA/Kyn." (PMID 32010121, 2019).
schistosomiasis (8 papers, 2012 to 2026). An infectious disease caused by parasitic trematodes of the genus Schistosoma that colonize human blood vessels and release eggs that can cause granulomatous reactions leading to acute (swimmer's itch or acute schistosomiasis syndrome) or chronic disease. "HSCs can also be activated during the chronic stage of schistosomiasis, and in turn, they can produce chemokines like CCL2, CCL3, and CXCL-10 following liver injury." (PMID 35839247, 2022).
scleroderma (8 papers, 2005 to 2025). Scleroderma is a rare autoimmune connective tissue disorder characterized by abnormal hardening of the skin and, sometimes, other organs. "The early expression of CCL2, CCL3 and CCL5 is also observed in a mouse model of scleroderma, with a subsequent rapid reduction of CCL5 and maintained high expression of CCL2 and CCL3." (PMID 33313931, 2021).
vitiligo (8 papers, 2009 to 2025). Generalized well circumscribed patches of leukoderma that are generally distributed over symmetric body locations and is due to autoimmune destruction of melanocytes. "Although elevated CCL2 expression in vitiligo fibroblasts has recently been linked to promoting type 2 cytokine secretion, the detailed mechanisms await further elucidation." (PMID 41310821, 2025). "Moreover, CCL2 addition into the naïve T polarization system promoted type 2 cytokines secretion, which represents a hallmark of vitiligo lesions." (PMID 36672151, 2023). "As the IFN-γ stimulated vitiligo fibroblasts displayed a T cell-regulatory transcription profile, we suspected that CCL2 and CCL8 might function through reshaping the T cell landscape." (PMID 36672151, 2023). "Indeed, in total, our data demonstrated that IFN-γ in the vitiligo lesions stimulates fibroblast’s expression of CCL2 and CCL8 through activating the JAK2/STAT1 signaling pathway." (PMID 36672151, 2023). "An in vitro experiment demonstrated that IFN-γ stimulation increased the expression of CCL2 and CCL8 by activating the JAK-STAT pathway in vitiligo fibroblasts." (PMID 38545113, 2024). "Meanwhile, recent evidence suggests that type 2 cytokines such as CCL2 and CCL8 are pivotal in shaping the vitiligo microenvironment." (PMID 38545113, 2024). "RNA sequencing revealed elevated chemokine CCL2 and CCL8 in vitiligo fibroblast, which may be regulated by the JAK-STAT signaling." (PMID 36672151, 2023).
Arrhythmia (7 papers, 2011 to 2025). Any cardiac rhythm other than the normal sinus rhythm. "However, the involvement of other genes, including CXCL8, FOS, CCL2, and MMP9, in aconitine-induced arrhythmias warrants further research." (PMID 35915792, 2022).
bacterial meningitis (7 papers, 2013 to 2024). Inflammation of the membranes surrounding the brain and spinal cord due to a bacterial infection. "In a study on bacterial meningitis, patients carrying the D148E polymorphism had reduced levels of IL-6, IL-1Ra, IL-8/CXCL8, and MCP-1/CCL2 compared with patients not harboring the polymorphism." (PMID 35296074, 2022).
cholangiocarcinoma (7 papers, 2016 to 2025). A carcinoma that arises from the intrahepatic biliary tree (intrahepatic cholangiocarcinoma) or from the junction, or adjacent to the junction, of the right and left hepatic ducts (hilar cholangiocarcinoma). "CCL2, also known as the inflammation-associated expression signature, was mostly derived from cancer-associated fibroblasts, which were components of the cholangiocarcinoma tumor microenvironment." (PMID 36065308, 2022). "The TWEAK/Fn14 signaling pathway may also increase the development and progression of cholangiocarcinoma niches through the downstream target CCL2." (PMID 36065308, 2022). "By binding to CCL2 messenger RNA, NAT10 escalates the expression level of the CCL2 protein within intrahepatic cholangiocarcinoma and in their extracellular matrix." (PMID 40588654, 2025). "The transcription factor EHF recruits and activates TAMs via the CCL2/CCR2 axis, remodeling the TME, and serves as a potential prognostic biomarker in cholangiocarcinoma." (PMID 41417432, 2025). "It has been reported that EVs derived from cholangiocarcinoma-educated bone marrow MSCs enhance the secretion of C-X-C motif chemokine ligand (CXCL)-1, C-C motif chemokine ligand 2 (CCL2), and IL-6, which affect cancer proliferation." (PMID 34944923, 2021).
cholestasis (7 papers, 2018 to 2025). Impairment of the bile flow caused by obstruction within the liver, or outside the liver in the bile duct system. "A recent study suggests that targeting the CCR2/CCL2 axis can limit monocyte recruitment and reduce fibrosis and cholestasis, offering a potential treatment approach for PSC." (PMID 38273376, 2024). "In the Mdr2−/− murine model of cholestasis, there was increased IFN-γ, CXCL10, and hepatic macrophages with elevated CCL2." (PMID 39859319, 2025). "Various molecules such as CCL2, CXCL1, CXCL2, and ICAM-1 have been reported to be important in neutrophil trafficking in the liver, which explains why liver injury occurs during cholestasis." (PMID 32701506, 2020).
chondrosarcoma (7 papers, 2010 to 2023). A malignant cartilaginous matrix-producing mesenchymal neoplasm arising from the bone and soft tissue. "Other studies on Huh7 cells and chondrosarcoma cells have also revealed a similar molecular mechanism in which CCL2 regulates MMP2 and MMP9 expression through the PI3K/Akt and NF-κB signaling pathways." (PMID 23941552, 2013). "Also, certain genes in the “biased” signature of dedifferentiated chondrosarcoma lung metastases, such as CCL2 and IL-8, were found to be significantly upregulated in primary tumors of nonsmall cell lung carcinoma with known history of lung metastases." (PMID 22448124, 2012). "The role of CCL2 in the activation of NF-κB has been demonstrated in a variety of cells, such as human chondrosarcoma cells, dorsal root ganglion neurons, but to the best of our knowledge, this was the first report that CCL2 could induce the activation of NF-κB in microglia." (PMID 28870240, 2017). "A similar effect in chondrosarcoma cells was described for CCL2, also known as monocyte chemoattractant protein (MCP)-1." (PMID 24901233, 2014).
cystic fibrosis (7 papers, 2014 to 2024). Autosomal recessive disorder caused by pathogenic variants in the CFTR gene (cystic fibrosis transmembrane conductance regulator), which encodes a chloride and bicarbonate channel expressed in epithelial cells, and follow the diagnosis criteria. "In addition, AZM significantly reduces the expression of the proinflammatory cytokine IL-1β and the chemokine C-C motif ligand (CCL)-2 and TNF-α in M1-induced cystic fibrosis alveolar macrophages in patients with cystic fibrosis." (PMID 24632748, 2014).
Dengue hemorrhagic fever (7 papers, 2012 to 2025). A serious condition caused by Dengue virus infection. "CCl2 is highly expressed in dengue hemorrhagic fever/dengue shock syndrome patients and is proposed to contribute to vascular permeability changes, possibly by weakening tight junctions of vascular endothelium cells." (PMID 25036379, 2014). "Increased levels of TNF-α, IL-1β, IL-4, IL-6, IL-8, IL-13, IL-15, macrophage migration inhibitory factor (MIF), and chemokines CCL2, CCL4, CCL5, and CXCL10 (IP-10) among others, have been reported in patients with dengue hemorrhagic fever (DHF) when compared to dengue fever (DF)." (PMID 29986388, 2018).
dilated cardiomyopathy (7 papers, 2013 to 2025). Cardiomyopathy which is characterized by dilation and contractile dysfunction of the left and right ventricles. "The chemokine (C-C motif) ligand 2 (CCL2) expressionlevel in the myocardium of patients with dilated cardiomyopathy (DCM) is higherthan that in normal myocardial tissue, correlating with the degree of impairedcardiac function." (PMID 40927089, 2025). "Shortly after, Kolattukudy and colleagues demonstrated in a transgenic murine model that CCL2 leads to increased myocardial leukocyte infiltration and to the phenotype of dilated cardiomyopathy." (PMID 27242392, 2016). "Altogether, these experiments show the important role of chemokines, especially of CCL2, in dilated cardiomyopathy and also in myocarditis, providing further clues supporting the existence of a common inflammatory pathway leading to the dilated cardiomyopathy phenotype." (PMID 27242392, 2016).